TNFRSF9 (TNF receptor superfamily member 9)
Diseases named in the same sentence as TNFRSF9 in open-access papers (continued):
Sharing a sentence is not in itself a finding about the gene and the disease.
infection (48 papers, 2010 to 2026). The state of being infected such as from the introduction of a foreign agent such as serum, vaccine, antigenic substance or organism. "The protein expression of seven proteins (CD8A, ST1A1, AXIN1, FGF-5, MMP-10, HGF, SIRT2) was significantly decreased and the protein expression of two proteins (MMP-1, TNFRSF9) was significantly increased in caspase-1-deficient cells compared to Cas9 cells following HK1651 infection." (PMID 40137780, 2025). "A group of Treg-signature genes (Areg, Arhpag20, Bub1b, Ccl12, Ccr5, Il1r1, Mki67 (Ki67) Ncf1, Nrp2, Tnfrsf9, Tcf19, Uhrf1, and Wnt3) were expressed at higher levels in IFNARfl/fl x Foxp3YFP-Cre mice than WT controls on day 5 Armstrong infection." (PMID 29672594, 2018). "At 24 h post-infection, knockdown of TNFRSF9 and SERPINI1 reversed the ability of IFN-γ to restrict survival of F. tularensis SchuS4 in THP-1 cells, as shown by CFU assay." (PMID 22359626, 2012). "Then we evaluated virulent F. tularensis SchuS4 infection of THP-1 cells in which six top hit genes (TNFRSF9, SERPINI1, HLA-DBR1, PLEK2, ATG5 and ATG16L1) were knocked down by individual lentiviral shRNA." (PMID 22359626, 2012). "Furthermore, PG-1 significantly downregulated key immune-associated genes, Cxcl9, Cxcl11, Tnfrsf9, Vdr and Ramp3, which were among the top 10 significantly upregulated genes post PCN033 infection." (PMID 41295668, 2025). "We first found that Tnfrsf9−/− mice were susceptible to C. albicans infection, whereas injection of anti-CD137 agonistic antibody protected the host from infection, suggesting that CD137 signaling is indispensable for innate immunity against C. albicans infection." (PMID 34068963, 2021). "Notably, the genes induced by the infection were enriched in multiple immune activation pathways, including cytokine-cytokine receptor interaction (e.g., Il22, Tnfrsf9 and Clcf1), JAK-STAT signaling pathway (e.g., Stat3), and chemokine signaling pathway (e.g., Ccr7) 33–35." (PMID 39013884, 2024). "We identified ten NK subgroup-specific marker molecules (Kcnj8, Cmah, Ccnd2, Cx3cr1, Thy1, Tnfrsf9, Zbtb20, Gng11, CD226, Egr3) from C0 to C9 and assessed their expression changes during infection using RT-qPCR." (PMID 40244063, 2025). "As unprimed Tnfrsf9−/− neutrophils have a marginal impairment in their phagocytotic capacity (data not shown), priming with CD137 signaling seems to occur during infection processes and contribute to elimination of invading C. albicans." (PMID 34068963, 2021). "Performing ProcartaPlex ELISA assays, we assessed whether the soluble TNF factors of these pathways (TNF-alpha, TNFSF9 and TNFRSF9) were secreted following infection and observed significantly increased secretion of TNF-alpha and TNFRSF9 from both USP7 and USP13 cells at 48 hpi." (PMID 40240536, 2025).
hematological malignancies (5 papers, 2012 to 2025). "Nevertheless, oOne of these networks includes 16 molecules in the category ‘Hematological Disease, Immunological Disease, and Cell Death’ and includes TNFRSF9 which may be involved in NF-κB, Akt, P38 MAPK and IL12 signaling pathways." (PMID 22359626, 2012).
adenocarcinoma (4 papers, 2019 to 2024). A common cancer characterized by the presence of malignant glandular cells. "The positive and negative correlation between the expression of APE1 and TNFRSF9+ Treg and CD8-C4-GZMK/CD8-C6-LAYN ratio were consistent in both adenocarcinoma subset and squamous cell subset respectively." (PMID 33676448, 2021).
cardiovascular disease (3 papers, 2015 to 2025). "Recent studies have revealed the important role of TNFRSF9 in cardiovascular disease." (PMID 40599317, 2025).
immune diseases (3 papers, 2022 to 2025). "Among those, six gene knockouts resulted in an immune disease, including Cd28, Ndfip1, Skap2, Tmem258, Tnfrsf1a, and Tnfrsf9." (PMID 35591976, 2022). "The colocalization of several TNF receptor superfamily members (TNFRSF1A, TNFRSF9, and TNFRSF14) further supports the development of drugs modulating TNF pathway, one of the main therapy lines for treating immune diseases." (PMID 35591976, 2022).
bacterial infection (2 papers, 2023). "In particular, we identified that gut F. nucleatum was positively associated with several serum proteomic markers which might be involved in host inflammation and immune activation related to bacterial infection (e.g., CXCL9, TNFRSF9)." (PMID 37237391, 2023).
blood cancer (2 papers, 2022 to 2024). "Among the proteins associated with risk of haematological cancers, we identified associations with risk of multiple blood cancers for members of the FC-receptor protein [FCRL1, FCRL2, FCRL3, FCRL5, FCRLB] and TNF receptor families [TNFRSF4, TNFRSF9, TNFRSF13B, TNFRSF13C, TNFSF13B, TNFSF13]." (PMID 38750076, 2024).
kidney disease (1 paper, 2024). "We also found, using the Olink proteomic platform, that TNF-α and TMAO enhanced the secretion of additional inflammatory-and growth mediators associated with kidney disease; VEGFA, GDNF, CDCP1, OPG, uPA, AXIN1, MMP-1, MMP-10, PD-L1, HGF, Flt3L, 4E-BP1, CD40, CASP-8, ADA, TNFRSF9, TWEAK44–61." (PMID 38643262, 2024).
TNFRSF9 also shares sentences with these, for which no sentence is quoted: Autoimmunity (22 papers); B cell lymphoma (15); viral infection (14); non-small cell lung carcinoma (11); lupus (10); hepatocellular carcinoma (7); infectious disease (7); influenza (7); myeloma (7); asthma (6); chronic lymphocytic leukemia (6); head and neck cancer (6); Hepatitis (6); inflammation (6); acute lymphoblastic leukemia (5); cervical carcinoma (5); experimental autoimmune encephalomyelitis (5); lung adenocarcinoma (5); neuroblastoma (5); renal cell carcinoma (5); metastatic melanoma (4); nasopharyngeal carcinoma (4); non-Hodgkin lymphoma (4); tuberculosis (4); acute coronary syndrome (3); Arthritis (3); chronic hepatitis (3); Cirrhosis (3); Crohn disease (3); esophageal cancer (3).
A further 134 diseases each share a sentence with TNFRSF9 in 3 papers or fewer.